ZHX2 (zinc fingers and homeoboxes 2)
Diseases named in the same sentence as ZHX2 in open-access papers (continued):
Sharing a sentence is not in itself a finding about the gene and the disease.
glioma (3 papers, 2021 to 2022). A benign or malignant brain and spinal cord tumor that arises from glial cells (astrocytes, oligodendrocytes, ependymal cells). "In glioma cells, ZHX2 binds to the promoter region of linc00707 and negatively regulates its expression, leading to glioma cells proliferation, migration and invasion, and vasculogenic mimicry (VM) formation." (PMID 36465389, 2022). "In glioma cells, it has been reported that ZHX2 interacts with HNRNPD and further regulates vasculogenic mimicry (VM) formation through the linc00707/miR-651–3p/SP2 pathway." (PMID 36232466, 2022). "In the present study, HNRNPD, linc00707, and specific protein 2 (SP2) were highly expressed, while zinc fingers and homeboxes 2 (ZHX2) and miR-651-3p were remarkedly downregulated in glioma tissues and cells." (PMID 33542193, 2021). "HNRNPD, linc00707, and SP2 knockdown or ZHX2 and miR-651-3p overexpression suppressed glioma cells proliferation, migration, and invasion and vasculogenic mimicry (VM) formation." (PMID 33542193, 2021). "The proliferation, migration, invasion, and VM formation ability of glioma cells in ZHX2(+) group were significantly lower than those in ZHX2(+)-NC group." (PMID 33542193, 2021). "Our study confirmed for the first time that HNRNPD and linc00707 are highly expressed in glioma tissues and cells, while ZHX2 and miR-651-3p are low expressed." (PMID 33542193, 2021). "The nude mouse xenograft model was used to further study the effects of HNRNPD, ZHX2, and linc00707 on the occurrence and development of glioma." (PMID 33542193, 2021). "First, we applied western blot to evaluate the expression of ZHX2, the results showed that ZHX2 is significantly downregulated in glioma tissues and cells, and the expression in high-grade glioma tissue is lower than that in the low one." (PMID 33542193, 2021). "Knockdown of HNRNPD, linc00707, and overexpression of ZHX2, miR-651-3p significantly inhibit the VM formation ability of glioma cells." (PMID 33542193, 2021). "Overexpression of ZHX2 significantly suppressed the VM forming ability of glioma cells." (PMID 33542193, 2021). "Meanwhile, we discovered that compared with knockdown of HNRNPD or overexpression of ZHX2 alone, the combination of the two could significantly inhibit the VM formation of glioma cells." (PMID 33542193, 2021). "Our study demonstrated that ZHX2 was underexpressed in glioma tissues and cells." (PMID 33542193, 2021). "The expression levels of ZHX2 and miR-651–3p were remarkedly reduced, while HNRNPD, linc00707, and specific protein 2 (SP2) expression were remarkedly increased in glioma." (PMID 36232466, 2022). "In this study, we first identified the endogenous expressions of HNRNPD, ZHX2, linc00707, miR-651-3p, and SP2 in glioma tissues and cells." (PMID 33542193, 2021). "Moreover, increasing the ZHX2 and miR-651–3p expression or decreasing the expression of HNRNPD, linc00707, and SP2 suppressed glioma cells’ proliferation, migration, invasion, and VM formation." (PMID 36232466, 2022). "The proliferation, migration, invasion, and VM formation ability of glioma cells in HNRNPD(−) + ZHX2(+)-NC group, HNRNPD(–)-NC + ZHX2(+) group, and HNRNPD(−) + ZHX2(+) group were significantly decreased, among which the HNRNPD(−) + ZHX2(+) group was the most significant." (PMID 33542193, 2021).
pancreatic cancer (3 papers, 2022 to 2024). "Integrative bioinformatics analyses reveal that a miRNA-related SNP (rs3802266-G), which creates a stronger binding site for miR-181-a-2-3p in 3’UTR of ZHX2 mRNA and consequently reduces ZHX2 expression, was significantly associated with increased risk of pancreatic cancer." (PMID 36465389, 2022).
renal cell carcinoma (3 papers, 2020 to 2023). "However, studies have also shown that ZHX2 is highly expressed in renal cell carcinoma cells, knockdown of ZHX2 inhibits the proliferation of renal cell carcinoma cells." (PMID 33542193, 2021). "For example, ZHX2 stimulates mitogen-activated protein kinase (MAPK) and drives cell growth and migration in the renal cell carcinoma (RCC) cell line." (PMID 37371558, 2023).
corticobasal degeneration (2 papers, 2021 to 2022). "Genetic variants of ZHX2 were found in two affected members of familial corticobasal degeneration, mutations of which were predicted to impair protein function." (PMID 34946922, 2021). "Exome sequencing in subjects with familial corticobasal degeneration (CBD) shows that mutations in ZHX2 gene may cause its structural changes, indicating the possible involvement of ZHX2 in corticobasal degeneration." (PMID 36465389, 2022).
glomerular disease (2 papers, 2023). "Adriamycin injection studies in 3 lines of podocyte-specific Zhx2-overexpressing transgenic rats show development of collapsing glomerulopathy beyond a certain threshold of Zhx2 overexpression." (PMID 37040185, 2023). "The insertion at Chr8: 122,533,694 was shared among patients with MCD and FSGS, and replication in a cultured podocyte cell line induced ZHX2 downregulation, adding to rapidly accumulating evidence of ZHX2 as an important disease modifier gene in primary glomerular diseases." (PMID 37040185, 2023). "While investigating human glomerular disease, low overall podocyte ZHX2 expression and increased nuclear ZHX1 were noted in MCD and low podocyte ZHX2 and increased nuclear ZHX2 and ZHX3 in FSGS." (PMID 37795536, 2023).
kidney cancer (2 papers, 2020 to 2023). Primary or metastatic malignant neoplasm involving the kidney. "USP13 mediates the deubiquitination of ZHX2 and promotes tumorigenesis in kidney cancer." (PMID 37259026, 2023).
lymph node metastases (2 papers, 2022 to 2025). "High ZHX2 expression implied an improved OS in patients with low frequency of lymph node metastases (N0 and N1)." (PMID 41480542, 2025).
acute kidney injury (1 paper, 2023). Sudden and sustained deterioration of the kidney function characterized by decreased glomerular filtration rate, increased serum creatinine or oliguria. "Cocktail D 3× dose induced substantially more severe cardiac, liver, and acute kidney injury in BALB/c compared with BALB/cJ mice, suggesting that the latter are protected by the Zhx2 hypomorph state." (PMID 37040185, 2023).
autoimmune disease (1 paper, 2023). A disorder resulting from loss of function or tissue destruction of an organ or multiple organs, arising from humoral or cellular immune responses of the individual to their own tissue constituents. "Briefly, some epitopes belonging to MEAF6, CHL1, and ZHX2 were reported to be potentially presented by either class I or class II HLA alleles for which a clear association with autoimmune diseases has been described." (PMID 37512859, 2023).
COVID-19 (1 paper, 2023). A disease caused by infection with severe acute respiratory syndrome coronavirus 2. "Whether the 3 other shared InDels increase or reduce ZHX2 expression in COVID-19 and collapsing variant FSGS patients will require CRISPR/Cas9 replication in cultured podocytes." (PMID 37040185, 2023). "p-STAT6 signaling, the other major mechanism studied in podocytes, was activated downstream of IL-4Rα by COVID-19 cocktails in the ZHX2+/+ podocytes and reduced in ZHX2hypo/hypo cells." (PMID 37040185, 2023). "At low doses, COVID-19 cocktails induced glomerular injury and albuminuria in zinc fingers and homeoboxes 2 (Zhx2) hypomorph and Zhx2+/+ mice to mimic COVID-19–related proteinuria." (PMID 37040185, 2023). "Whereas the Common Cold cocktail induced albuminuria selectively in the Zhx2 hypomorph state, simply substituting ACE2 for ICAM-1 in Common Cold cocktails (COVID-19 Cocktail A) induced albuminuria in Zhx2+/+ mice." (PMID 37040185, 2023).
dementia (1 paper, 2021). Loss of intellectual abilities interfering with an individual's social and occupational functions. "Since ZHX2 is also associated with cortical neuronogenesis, it may be associated with the progression to dementia." (PMID 34946922, 2021). "SNPs in ZHX2 and ERP29 were also associated with dementia in PD." (PMID 34946922, 2021). "Few clinical studies have investigated the role of ZHX2 and ERP29 in PD or dementia." (PMID 34946922, 2021). "ZHX2 and ERP29 also showed correlations with dementia in PD." (PMID 34946922, 2021).
fatty liver disease (1 paper, 2022). A reversible condition wherein large vacuoles of triglyceride fat accumulate in liver cells via the process of steatosis. "The involvement of ZHX2 in fatty liver disease is further confirmed by a recent study showing that Zhx2 deficiency in hepatocytes exacerbates NASH progression by transcriptional activation of Pten." (PMID 36465389, 2022).
hemangioblastoma (1 paper, 2024). "ZHX2 was ubiquitinated in Scl+hemangioblastoma-like cells after the transfer of the VHL expression vector into these cells." (PMID 39850947, 2024). "The expression of ZHX2 in CNS hemangioblastoma tissues was shown." (PMID 39850947, 2024).
hepatic (1 paper, 2025). "Second, we discover that the transcriptional repressor Zbtb20 acts as a critical suppressor of Zhx2 expression, forming a regulatory axis that plays a crucial role in liver injury responses and offers a novel molecular insight into hepatic disease progression." (PMID 40589742, 2025).
Hepatic fibrosis (1 paper, 2023). The presence of excessive fibrous connective tissue in the liver. "In mice, ZHX2 is a transcription factor with demonstrated centrality in liver metabolism, including lipid accumulation, enhanced inflammation, and hepatic fibrosis." (PMID 36980820, 2023).
liver diseases (1 paper, 2022). "ZHX2 (zinc fingers and homeoboxes 2) is the transcription factor that promotes the transcription of phosphatase and tensin homolog (PTEN) and alleviates NASH (advanced liver diseases)." (PMID 36005139, 2022).
metastatic tumors (1 paper, 2023). "Consistently, IHC/IF results showed that CDH1 and ZHX2 protein levels were negatively correlated in both mouse and human primary and metastatic tumors." (PMID 37460540, 2023).
osteosarcoma (1 paper, 2025). A usually aggressive malignant bone-forming mesenchymal neoplasm, predominantly affecting adolescents and young adults. "METTL3/m6A/IGF2BP1-mediated stabilization of melanoma cell adhesion molecule (MCAM) and zinc-fingers and homeoboxes 2 (Zhx2) mRNA suppressed apoptosis of osteosarcoma cells and RCC cells." (PMID 40584294, 2025).
renal carcinoma (1 paper, 2020). A carcinoma arising from the epithelium of the renal parenchyma or the renal pelvis. "Such as the degradation of HIF‐1α and ZHX2 can be inhibited in VHL deficiency renal carcinoma." (PMID 32780537, 2020).
schizophrenia (1 paper, 2019). A major psychotic disorder characterized by abnormalities in the perception or expression of reality. "GAMuT found ZHX2, on chromosome 8, to be strongly associated with BDI (P = 2.73 × 10−6), when using genotype weights based on estimated log odds ratios from the PGC GWAS for schizophrenia." (PMID 31101869, 2019).
thyroid tumours (1 paper, 2022). "Here, we found that low expression of ZHX2 was associated with poor prognosis in patients with thyroid tumours." (PMID 35151335, 2022). "To determine the protein levels of ZHX2 in thyroid tumours, we employed western blotting for collected thyroid tumour samples." (PMID 35151335, 2022). "The expression of S100A14 negatively correlated with ZHX2 expression in human thyroid tumour specimens." (PMID 35151335, 2022). "Therefore, targeting ZHX2 and S100A14 signalling may be a useful strategy to inhibit thyroid tumour progression." (PMID 35151335, 2022).
tumor (43 papers, 2013 to 2025). "In HCC, Zhx2 deletion promotes pro-tumor TAM phenotypes, and lower Zhx2 levels in TAMs are linked to poor survival in patients." (PMID 40764998, 2025). "The high expression of ZHX2 was also significantly associated with tumor stage, and poor patient survival." (PMID 37460540, 2023). "Further studies confirmed that ZHX2 expression levels and tumor-suppressive activities were inhibited by HBV-encoded proteins, particularly HBx." (PMID 36232466, 2022). "As an HCC-associated tumor suppressor, zinc fingers and homeoboxes 2 (ZHX2) is negatively associated with SREBP-1c in HCC cell lines and human specimens." (PMID 35912181, 2022). "As an HCC-associated tumor suppressor, ZHX2 is found to be hepatoprotective by reducing liver lipid levels in a high-fat diet-fed rodent model." (PMID 36232466, 2022). "On the other hand, the expression of ZHX2, encoding the zinc finger and homeoboxes 2 protein, a liver-enriched tumor suppressor known to inhibit HBV transcription was found enriched in P2 cells." (PMID 34290079, 2021). "Many studies including ours demonstrate ZHX2 as an HCC-associated tumor suppressor." (PMID 31740790, 2020). "Manipulating the deficiency of ZHX2 could enhance tumor progression and liver CSC stemness." (PMID 36232466, 2022). "Pharmacological inhibition of Hpo/MST1/2 kinase activity inhibited p65/ZHX2 cooperativity, leading to diminished NF-κB target gene expression and inhibited ccRCC tumor growth, which can be alleviated by increasing the activity of ZHX2 or p65." (PMID 40120683, 2025). "Pharmacological inhibition of Hippo/MST1/2 kinase activity inhibited p65/ZHX2 cooperativity, leading to diminished NF-κB target gene expression and inhibited ccRCC tumor growth, which can be alleviated by increasing the activity of ZHX2 or p65." (PMID 38979373, 2025). "Tumor cells from ccRCC patients with VHL loss-of-function mutations typically show increased abundance and nuclear localization of ZHX2." (PMID 39850947, 2024). "Tumor cells from ccRCC patients with VHL loss-of-function mutations demonstrate increased abundance and nuclear localization of ZHX2." (PMID 38396737, 2024). "Further studies on the role and mechanism of ZHX2 in different tumors will provide more potential therapeutic strategies for tumor treatment." (PMID 37460540, 2023). "Studies have shown that ZHX2 plays a tumor suppressor role in hepatocellular carcinoma by transcriptional repressing the key cell cycle regulators, cyclin E and cyclin A." (PMID 37460540, 2023). "ZHX2 depletion in MDA-MB-231 cells significantly reduced the number of visible metastatic nodules on the lung surface of tumor-bearing mice." (PMID 37460540, 2023). "During carcinogenesis of HCC, ZHX2 also plays a tumor-inhibitory role through dysregulating HBV X protein (HBx)." (PMID 36232466, 2022). "Elevating ZHX2 expression attenuated liver CSCs transformation from the initiation of tumor formation, self-renewal, and sorafenib-resistance." (PMID 36232466, 2022). "ZHX2 not only inhibits tumor growth but also suppresses tumorigenesis and tumor development through multiple mechanisms." (PMID 36465389, 2022). "The tumor suppressor role of ZHX2 has also been demonstrated in many other types of tumors including hematological tumors and solid tumors." (PMID 36465389, 2022). "ZHX2 expression is significantly decreased in tumor tissues of HBV-positive HCC and livers of HBV-transgenic mice." (PMID 36232466, 2022). "The contribution of ZHX2 in the dysregulation of tumor-infiltrating NK cells strengthens ZHX2 as an immune checkpoint regulating NK cells." (PMID 36465389, 2022). "Together, accumulated data demonstrate the critical role of ZHX2 in cancer, either as a tumor suppressor or as an oncogene." (PMID 36465389, 2022). "Consistently, significantly lower expression of ZHX2 mRNA in tumours was confirmed by RT-qPCR analysis." (PMID 35151335, 2022).
tumor (continued). "Functional studies showed that manipulating the deletion of ZHX2 inhibits TNBC tumor growth and metastasis." (PMID 36232466, 2022). "Despite the apparent tumor repression role of ZHX2 in HCC and other cancer types, a number of studies have illustrated that ZHX2 can function as an oncogene." (PMID 36465389, 2022). "Subsequent studies further illustrated the critical role of ZHX2 as a tumor suppressor in HCC with a variety of etiologies, including NASH-related HCC and HBV-related HCC." (PMID 36465389, 2022). "All these data reveal a widespread restriction role of ZHX2 in tumor development at multiple dimensions, including tumor cell proliferation, metastasis, stemness, and chemotherapeutic resistance." (PMID 36465389, 2022). "(H, I) Immunoblot of cell lysates (H) and tumor growth (I) of HCC70-luc cells expressing Dox-inducible control or ZHX2 shRNAs (Teton Ctrl, sh43, 45)." (PMID 34779768, 2021). "In accordance with the cell line data, we found that ZHX2 was upregulated in most of tumor tissues compared to normal, coinciding with decreased pVHL protein levels in respective tumor tissues." (PMID 34779768, 2021). "Consistent with results above, Dox chow led to significantly decreased TNBC tumor growth over time and decreased ZHX2 protein levels in tumors." (PMID 34779768, 2021). "(A, B) Immunoblot of cell lysates (A) and tumor growth (B) of MDA-MB-231-luc cells expressing doxycycline (Dox)-inducible control or ZHX2 shRNAs (Teton Ctrl, sh43, 45)." (PMID 34779768, 2021). "We found that ZHX2 depletion significantly decreased tumor growth overtime, as well as reduced tumor burden retrieved from tumor-bearing mice compared to control mice upon necropsy." (PMID 34779768, 2021). "(A) The percentage of tumor samples with ZHX2 (top) or MYC (bottom) focal amplification across cancer types." (PMID 34779768, 2021). "The transcriptional repressor zinc finger homeobox 2 (ZHX2) is reported to regulate tumor progression in several human cancers, although little is known about its role in gastric cancer (GC)." (PMID 33837660, 2021). "These pieces of evidence suggest that ZHX2 acts as a tumor suppressor or oncogene in a context-dependent manner." (PMID 34779768, 2021). "We found consistent results in terms of ZHX2 knockdown, in vitro growth, as well as in vivo tumor growth." (PMID 34779768, 2021). "In summary, their research proved that ZHX2 was involved in this regulative network and functioned as a tumor suppressor in B-cells malignant tumor as well." (PMID 32382017, 2020). "It is also found that ZHX2 promotes cell survival and reduces apoptosis in non‐tumor cells, such as macrophage." (PMID 32780537, 2020). "Zinc finger and homeoboxes 2 (ZHX2) is also a liver-enriched transcriptional repressor in adult hepatocytes and a tumor suppressor." (PMID 32019103, 2020). "As expected, the number of tumor nodes in mice injected with AAV-ZHX2 were significantly less compared with the control mice, suggesting that ZHX2 suppresses the progression of NAFLD to HCC." (PMID 31740790, 2020). "The expressions of ZHX1 and ZHX3 in most ccRCC tissues were lower than in paired non-tumor tissues, whereas ZHX2 expression was higher in most ccRCC tissues." (PMID 28152006, 2017). "Furthermore, this study demonstrated that ZHX2 promoted ccRCC tumor growth by promoting NF-κB pathway activity." (PMID 38979373, 2025). "Hence, ZHX2 counteracts the anti-tumor activity of PIs in resistant cases, and its higher expression is accompanied by less promising clinical outcomes in MM patients." (PMID 38331801, 2024). "Compared to the control group, I-125 significantly inhibited tumor volume, which could be compromised when ZHX2 was downregulated; the change in tumor weight showed a similar result." (PMID 37563132, 2023). "Notably, ZHX2 expressions were amplified in diverse areas of the tumor mass and negatively correlated with E-cadherin expressions in patients with TNBC, which is associated with poor TNBC prognosis." (PMID 37460540, 2023).